EGF (epidermal growth factor)
Diseases named in the same sentence as EGF in open-access papers (continued):
Sharing a sentence is not in itself a finding about the gene and the disease.
breast carcinoma (continued). "Here we report on our findings for biomarkers previously related to breast cancer, epidermal growth factor (EGF), transforming growth factor-beta 1 (TGF-β1), and adiponectin." (PMID 24252368, 2013). "VEGF is closely associated with the promotion of angiogenesis, increment of micro-vessel density and with early relapse in primary breast cancer, yet clinical trials of agents that target either EGF or VEGF signaling pathways alone have been disappointing." (PMID 24138843, 2013). "The current study sought to determine the ZEB1/MYB/proliferation interplay in the epidermal growth factor (EGF)-responsive PMC42 model of breast cancer EMT." (PMID 24283570, 2013). "This set of experiments indicates that both mitogenic and migratory signaling of EGF requires AR/Src complex assembly in human prostate and mammary cancer-derived cells." (PMID 24130806, 2013). "Treatment of breast cancer cells with EGF induces robust PR Ser294 phosphorylation and deSUMOylation." (PMID 22697792, 2012). "In the present study, we examined the effect of EBP50 overexpression and knockdown on EGF-induced breast cancer cell proliferation." (PMID 22476347, 2012). "In fact, the PH domain of GEP100 was identified to bind directly to Tyr1068/1086-phosphorylated EGFR and was required for EGF-stimulated Arf6 activation in MDA-MB-231 breast cancer cells." (PMID 22701712, 2012). "Another recent study has shown that down-regulation of Akt1 enhanced epidermal growth factor (EGF)-stimulated cell migration in MCF-10A breast cancer cells." (PMID 22570727, 2012). "Taken together, these results reveal that EBP50 can block EGF-induced EGFR phosphorylation in breast cancer cells." (PMID 22476347, 2012). "Our results showed that EBP50 can inhibit EGF-stimulated breast cancer cell proliferation and EGFR pathway activation, supporting a role for EBP50 in inhibiting EGF-induced cell proliferation by blocking EGFR phosphorylation in breast cancer cells." (PMID 22476347, 2012). "Breast tumor kinase (Brk) and ERK5 were recently shown to act as important mediators of migration in breast cancer cells downstream the EGF and the HGF receptors." (PMID 23028720, 2012). "Upregulation of TTP expression by EGF described in this paper reveals unexpected influence of EGF on breast cancer development." (PMID 22433566, 2012). "It has been shown that the PH domain of GEP100 is associated with phosphorylated Tyr951 of VEGFR2, and its PH domain was also reported to bind to certain phosphorylated tyrosines on EGFR, and mediate EGF-stimulated breast cancer cell invasion." (PMID 22701712, 2012). "The current study has characterized mechanisms regulating Ca2+ influx in MDA-MB-468 human breast cancer cells and assessed alterations in Ca2+ signaling as a consequence of EGF-induced EMT." (PMID 22666335, 2012). "Our research focused on the mechanisms of TTP transcript induction by EGF in a cellular model of human breast cancer, using MCF-7 cell line." (PMID 22433566, 2012). "In accordance, it has been recently reported that SK1 and SK2 are equally required for epidermal growth factor-induced migration of breast cancer cells and TGFβ-induced migration and invasion of esophageal cancer cells." (PMID 22788716, 2012). "PLC has been shown to be required for triggering the first but not the second wave of actin polymerization through the regulation of cofilin activity in breast cancer cells stimulated with EGF." (PMID 22279563, 2012). "Here, we utilized a powerful analytical method called Gene Set Enrichment Analysis (GSEA) focusing on several biological pathways: EGF, Stathmin, HER2, BRCA1,Homologous Recombination, which are associated with breast cancer progression." (PMID 22595006, 2012). "In the present study we investigated the migratory activity of M13MDA435-1 and -3 hybrid clones and their parental cells (M13SV1-EGFP-Neo breast epithelial cells and MDA-MB-435-Hyg breast cancer cells) in response to EGF and SDF-1α." (PMID 22487193, 2012).
breast carcinoma (continued). "In breast carcinomas, macrophages and cancerous cells form a paracrine loop involving epidermal growth factor (EGF) and colony stimulating factor-1 (CSF-1) to augment chemotaxis and intravasation." (PMID 22482059, 2012). "Here we sought to assess changes in store-operated Ca2+ entry in a well characterized model of EMT mediated by EGF in MDA-MB-468 breast cancer cells." (PMID 22666335, 2012). "Taken together, these results suggested that EBP50 inhibited EGF-induced cell proliferation in breast cancer cells." (PMID 22476347, 2012). "To study the effect of EBP50 expression on EGF-stimulated cell proliferation and EGFR-mediated signal transduction pathways in breast cancer cells, we combined EBP50 gain-of-function and loss-of-function studies." (PMID 22476347, 2012). "Taken together, our data shows that EBP50 can suppress EGF-induced proliferation of breast cancer cells by inhibiting EGFR phosphorylation and blocking EGFR downstream signaling in breast cancer cells." (PMID 22476347, 2012). "One related to brain metastasis is the recent report of EGF promoting heparanase function and Topoisomerase I localization in brain metastasizing breast cancer cells." (PMID 23217186, 2012). "It has also been shown that the assembly of the EGFR/AR/ER/Src signaling complex is crucial for proliferation of prostate and breast cancer cells triggered by androgens, estrogens and/or EGF." (PMID 22922989, 2012). "Here we characterized Ca2+ influx, in particular mechanisms important for store-operated Ca2+ entry, during EGF-mediated EMT in human breast cancer cells and the downstream signaling events regulated by these Ca2+ influx pathways." (PMID 22666335, 2012). "EGF produced by macrophages promotes migration of neoplastic cells into hematogenous vasculature through its interaction with EGF receptor expressed on breast cancer cells." (PMID 22482059, 2012). "It was reported that EGF signaling induced claudin-2 expression which promoted colonization of mammary tumor cells." (PMID 22824143, 2012). "It has been reported that PIPKIγ is required for EGF-stimulated migration of MDA-MB-231 human breast cancer cells and HeLa human ovarian cancer cells." (PMID 21931851, 2011). "We have also discovered that GPR54 directly complexes with EGFR, and that stimulation of breast cancer cells with either Kp-10 or EGF regulates the endocytosis of both GPR54 and EGFR." (PMID 21738726, 2011). "Epidermal growth factor (EGF) is an important growth factor associated with cell proliferation and tumorigenesis in breast cancer." (PMID 21980430, 2011). "By combining affinity capture using matured antibodies to SHC1 with mass spectrometry, we identified seven known binding partners and two known SHC1 phosphorylation sites in epidermal growth factor (EGF)-stimulated human breast cancer epithelial cells." (PMID 21704603, 2011). "The acquisition of a new suite of cell surface purinergic receptors is a feature of EGF-mediated EMT in MDA-MB-468 breast cancer cells." (PMID 21850275, 2011). "In contrast, our results show that EGF treatment resulted in a significant increase in the production of ROS in breast cancer cell line MDA-MB-231." (PMID 23554696, 2011). "The anti-epidermal growth factor (anti-EGF) receptor antibody trastuzumab has revolutionised the treatment of patients with EGF receptor-positive breast cancer." (PMID 21982514, 2011). "In total, the PDGF and EGF pathways' impacts on the breast cancer networks added to pathway analysis." (PMID 22123172, 2011). "In summary, this study identifies a novel signaling pathway that accounts for EGF-induced breast cancer cell migration, including activation of Rac1, generation of ROS, subsequent activation of PI3K/Akt and PAK1." (PMID 23554696, 2011). "EGF stimulates the proliferation of breast cancer cells by binding to EGFR which is one of the oncogenes of breast cancer." (PMID 22174624, 2011).
breast carcinoma (continued). "Evidence for cross-talk between NGF or EGF and the estradiol pathways has also been demonstrated, and in this regard, the anti-oestrogenic drug tamoxifen can inhibit proliferation by EGF or NGF on MCF-7 breast cancer cells." (PMID 21241485, 2011). "In vitro some cell lines undergo EMT in response to EGF stimulation, such as the human breast cancer cell line MDA-MB-468." (PMID 21850275, 2011). "NHE-1, in breast cancer cells stimulated with EGF, has also been located at invadopodia protrusion sites where the exchanger was shown to be involved in acidification of the extracellular microenvironment, resulting in focal ECM degradation." (PMID 22216126, 2011). "Previously, we reported that Brk promotes increased breast cancer cell proliferation and migration in response to the erbB ligands, EGF and heregulin, in part via Brk-dependent signaling to p38 MAPK." (PMID 21923922, 2011). "This promoter is transactivated by the growth factors nerve growth factor (NGF) and epidermal growth factor (EGF) and the hormone estradiol, all of which are known to promote the proliferation and/or survival of breast cancer cells." (PMID 21241485, 2011). "Brk-dependent signaling to p38 MAPK was recapitulated by Brk overexpression in the HC11 murine mammary epithelial cell (MEC) line and human MEC, while Brk knock-down in breast cancer cells blocked EGF-stimulated p38 signaling." (PMID 21923922, 2011). "In mouse models of invasive breast cancer, macrophage-secreted epidermal growth factor (EGF) stimulates growth and migration of mammary tumor cells, which in turn secrete colony stimulating factor-1 (CSF-1) to recruit additional macrophages to the tumor site." (PMID 21699731, 2011). "While Neuregulin-1 (NRG1) and EGF growth factors induce an increase of hMena expression, Herceptin treatment down-regulates hMena in breast cancer cell lines overexpressing HER2." (PMID 21209853, 2010). "The SNIP protein is tyrosine phosphorylated upon integrin-dependent adhesion or EGF treatment, with a potential role as a downstream effector of cell matrix and growth factor signaling that suppresses tumorigenic properties of breast cancer cells." (PMID 20932292, 2010). "17β-Estradiol (E2) and epidermal growth factor (EGF), two agents that can increase intracellular oxidative stress, are also strongly linked to the development of breast cancer." (PMID 20809984, 2010). "This isoform undergoes phosphorylation upon long term stimulation with EGF, associated with p44/42 MAPK activation and with an increased proliferation rate in breast cancer cell lines." (PMID 21209853, 2010). "As well, low EGF levels present in low serum-containing medium stimulated growth of human breast cancer cell lines A431 and BT20, expressing high ERα levels, while high EGF concentrations inhibited cell growth." (PMID 20809984, 2010). "Further studies linked Brk signaling to p38 MAPK activation as required steps for EGF and heregulin-β1-induced T47D breast cancer cell migration." (PMID 20687930, 2010). "Whilst an attractive model, other studies report that IGFBP3 can potentiate EGF-stimulated proliferation in MCF10A cells and that IGFBP3 expression is associated with growth stimulation of T47D human breast cancer cells." (PMID 20840765, 2010). "ERα levels can be modulated by EGF, which was shown to increase oxidative DNA damage in mammary tumor cells coincident with increased malignancy." (PMID 20809984, 2010). "Coordinated expression of CSF-1 in macrophages and epidermal growth factor (EGF) in mammary tumor cells resulted in increased myeloid cell invasion into mammary tumors." (PMID 20490273, 2010). "Consistently, both Tyr1068 and Tyr1086 become heavily phosphorylated in breast cancer cells upon EGF stimulation." (PMID 19416474, 2009).
breast carcinoma (continued). "EGF plays an important role in the development of the normal breast and is also a key player in the progression of breast carcinomas, and as previously shown, EGF at 10 ng/ml over 72 h can induce EMT in PMC42-LA cells." (PMID 19604397, 2009). "Advanced T-stage breast cancer (T3 and T4) showed increased serum levels of EGF and ApoH, but decreased levels of A1AT." (PMID 19400944, 2009). "We showed here that MSC secreted IL-6 is key to the growth of the Skov-3 ovarian tumor model while we showed previously the importance of MSC-secreted EGF to the ERα-positive breast cancer model." (PMID 19352430, 2009). "Among the 35 analytes, EGF, sCD40L and proApoA1 showed higher serum concentrations in breast cancer patients than in normal subjects." (PMID 19400944, 2009). "High levels of circulating EGF were reported in serum samples from HER2-negative breast cancer patients, although increased levels of IL-8 were consistently noted in serum samples from metastatic breast cancer patients." (PMID 19400944, 2009). "Firstly, Gab2 is frequently over-expressed in human breast cancer cell lines and primary tumours and becomes tyrosine phosphorylated in these cells in response to EGF, insulin and bFGF stimulation." (PMID 19737390, 2009). "We showed previously that EGF stimulation of breast cancer cells leads to phosphorylation of STAT5b on Y699 and subsequent transcriptional activity." (PMID 19630967, 2009). "EGF induces EMT in the breast cancer cell line PMC42-LA and the kinase inhibitor staurosporine (ST) induces EMT in embryonic neural epithelial cells, with F-actin de-bundling and disruption of cell-cell adhesion, via inhibition of aPKC." (PMID 19604397, 2009). "We have shown that co-overexpression of GEP100 and Arf6 in MCF7 breast cancer cells induces invasiveness, which is substantially dependent on EGF stimulation." (PMID 19416474, 2009). "Sharing a common ErbB/HER receptor signaling pathway, heregulin (HRG) induces differentiation of MCF-7 human breast cancer cells while epidermal growth factor (EGF) elicits proliferation." (PMID 19925682, 2009). "Among the cytokines and growth factors included in this study, EGF was the only marker increased in the serum of breast cancer patients and correlated with advanced T stage." (PMID 19400944, 2009). "Depletion of cofilin activity abolishes the barbed-end increase at the cell periphery of metastatic MTLn3 breast carcinoma cells induced by epidermal growth factor." (PMID 19290054, 2009). "The breast ductal epithelium is a complex environment therefore it is unlikely that EGF initiates or acts alone in regulating breast cancer cell invasion." (PMID 19604397, 2009). "We also compared our method with various reverse-engineering algorithms on experimental data of MCF-7 breast cancer cells stimulated with two ErbB ligands, EGF and HRG." (PMID 19386091, 2009). "In particular we demonstrated that PI3K-mediated PLCγ1 activation is required for epidermal growth factor-induced migration of breast cancer cells." (PMID 20011604, 2009). "We have previously shown the epithelial-like human breast carcinoma PMC42-LA subline undergoes an EMT-like change in response to EGF treatment, and in response to factors secreted by human breast carcinoma-derived stromal cells." (PMID 19604397, 2009). "We previously showed that stimulation of MCF-7 breast cancer cells with EGF and HRG resulted in very similar early transcription profiles up to 90 min, however subsequent cellular phenotypes differed." (PMID 19925682, 2009). "This is a novel report on the role of S100A7 in EGF-induced signaling in breast cancer cells and in osteoclast formation." (PMID 18320059, 2008). "Experiments in our breast cancer cell lines showed that EGF treatment significantly increased phosphorylation of ERK as measured by immunofluorescence." (PMID 18534028, 2008).
breast carcinoma (continued). "We found that Vav3 activates ERα partially via PI3K-Akt signaling and potentiates EGF effect for cell growth and ERα activation in breast cancer cells." (PMID 18518979, 2008). "We have seen increased expression of S100A7 in two breast cancer cell lines following EGF stimulation." (PMID 18320059, 2008). "We found that S100A7-downregulated breast cancer cells exhibited a reduction in EGF-induced chemotaxis and invasion on matrigel-coated transwells." (PMID 18320059, 2008). "We also characterized EGFR's influence on S100A7 expression and its role in the EGF-induced metastasis and invasion of breast cancer cells." (PMID 18320059, 2008). "In agreement with its effects on estrogen-independent growth in breast cancer cells, overexpression of Vav3 potentiated EGF-stimulated ERα activation." (PMID 18518979, 2008). "EGF has been found to stimulate a variety of tissues including normal rodent breast tissue and rodent breast cancer and human breast epithelial cells in culture and fibridomas." (PMID 18179684, 2008). "We had comprehensive SNP coverage of the entire ESR1 and EGF genes and were thus able to study if there were any common variants in the genes that showed an association with breast cancer risk, NPI or breast cancer survival." (PMID 18271972, 2008). "We genotyped 157 SNPs in ESR1 and 54 SNPs in EGF using a population-based case-control study, which included 1,590 breast cancer cases and 1,518 controls." (PMID 18271972, 2008). "Certain breast carcinoma cell lines (e.g. MDA-MB-231) have been reported to over express the receptor for EGF." (PMID 17662123, 2007). "Using the advantages of this microfluidic platform, we have developed real-time optical assays to investigate cell proliferation and death in mouse NPCs, and chemotaxis of MDA-MB-231 breast cancer cells exposed to EGF gradients." (PMID 17883868, 2007). "Ostander and colleagues have shown that Brk knockdown decreases cell growth as well as epidermal growth factor-induced (or heregulin-induced) migration of breast cancer cells." (PMID 17997837, 2007). "In ER-positive and ER-negative breast cancer cell lines and in primary cell cultures derived from patient tumours, both 17β-oestradiol and EGF increased expression of phospho-Raf and phospho-ERK1/2." (PMID 16805920, 2006). "Of interest, pertussis toxin also attenuated EGF-induced breast cancer cell proliferation and phospho-Raf expression." (PMID 16805920, 2006). "The ability of growth factors bFGF and EGF to induce PEA3 expression in primary breast cancer cells derived from patient tumours was investigated by Western blotting." (PMID 17060941, 2006). "Our results present an overview of gene expression changes after perturbation of ZR-75-1 breast cancer cells with treatment with oestrogen or EGF or by the overexpression of BCAR genes." (PMID 15642172, 2005). "In the present study, we designed an approach to block the EGF-induced cell migration of EGFR/c-erbB-2-positive breast cancer cells by using protein-based PLC-γ1 inhibitors." (PMID 14710234, 2004). "We have previously reported that oestrogen inhibits erbB-2 mRNA and protein expression in breast cancer cells, while epidermal growth factor (EGF) treatment has been shown to decrease p185erbB-2 levels in normal mouse mammary epithelial cells." (PMID 7526884, 1994). "In the present work, we studied the effect of oestrogen and EGF on erbB-2 expression in oestrogen-responsive breast cancer cells." (PMID 7526884, 1994). "We have examined the expression of receptors for epidermal growth factor (EGFR) by the ZR-75-1 human breast cancer cell line and tamoxifen resistant (ZR-75-9al 8 microM) and oestrogen independent/tamoxifen sensitive (ZR-PR-LT) variants." (PMID 1616857, 1992). "The cellular content of receptors for epidermal growth factor (EGF) was measured in different histological subgroups of human mammary carcinomas." (PMID 3017397, 1986).